ICAM2 (intercellular adhesion molecule 2)
Diseases named in the same sentence as ICAM2 in open-access papers (continued):
Sharing a sentence is not in itself a finding about the gene and the disease.
tumor (continued). "The intercommunication between LFA-1 on tumour cells and ICAM-1 (or alternative ligands, ICAM-2/ICAM-3/ICAM-4/JAM-1) on other cells in the local vicinity triggers signalling through several pathways on each side." (PMID 27447568, 2016). "Unlike the matched adjacent non-tumor tissues within cohort 1, there was a significant decrease in ICAM2 expression in GC tissues." (PMID 37759298, 2023). "Six weeks after mammary fat pad injection in the 100 tumor cells, 25% of mice in the ICAM2-overexpressing group reported tumor formation, whereas no tumor was detected in the vector control group until the tenth week." (PMID 37620448, 2023). "As confirmed by histopathological data, tumor cells suspended in the CSF compartment of the lumbar spine were detected in the scramble group but not in the ICAM2-downregulating group." (PMID 37620448, 2023). "Histopathological data demonstrated that tumor cells can infiltrate into the leptomeningeal space that were detected in the ICAM2-overexpressing group but not in the vector control group." (PMID 37620448, 2023). "Changes in tumor EC properties under inflammatory conditions with direct consequences for leukocyte tumor infiltration are altered expression of P- and E-selectin, ICAM-1 and ICAM-2, VCAM-1 and CD31/PECAM-1." (PMID 35216427, 2022). "Similarly, co-expression of Intercellular Adhesion Molecule-2 (ICAM-2) and chemokine C-X-C motif ligand 17 (CXCL17) elicits anti-tumor immune responses and suppresses tumor growth." (PMID 26697524, 2015). "Because cell adhesion molecules and the actin cytoskeleton have been reported to regulate tumorigenic potential, we injected SK-N-ASpIRESneo and SK-N-ASpIRES.ICAM2 cells subcutaneously into SCID mice (5 mice per group, bilateral flank injections) and observed the mice for tumor development." (PMID 18978946, 2008). "Since both ICAM-2 and control transfectants readily formed subcutaneous tumors, we concluded that ICAM-2 was unlikely to be acting as a tumor suppressor." (PMID 18978946, 2008). "However, despite the multiple proteins and pathways known to be affected by cell adhesion molecules in general and ICAM-2 in particular, complete membrane-to actin linkages that regulate CAM function in tumor cells have been difficult to identify." (PMID 18978946, 2008). "Moreover, TECs also interacted with T/NK cells via ICAM1/ICAM2-(ITGAL + ITGB2), which might contribute to immune cell infiltration and effective anti-tumor immune response." (PMID 39093451, 2024). "The functional significance of the interactions of ICAM-2 with actin linker proteins in tumor cells is largely unknown, with the exception of our recent observation that the interaction of ICAM-2 with α-actinin is essential to ICAM-2-mediated suppression of the metastatic potential of NB cells." (PMID 23714211, 2013). "Inhibition of tumor cell motility by ICAM-2 has not been reported previously." (PMID 18978946, 2008). "Notably, the contrast between results for ICAM-2 expression of immature neuroblasts in the stage 4 tumor compared to the 4S tumor indicates that ICAM-2 is not simply a differentiation marker." (PMID 18978946, 2008). "However, the expression and function of ICAM2 in tumor cells has not been well investigated." (PMID 27556181, 2016).
cancer (17 papers, 2008 to 2025). A tumor composed of atypical neoplastic, often pleomorphic cells that invade other tissues. "ICAM2 has similarly shown both pro- and anti-tumoral associations depending on cancer type and context." (PMID 40659866, 2025). "Similarly, it was indicated that ICAM-1 and ICAM-2 suppression was positively correlated with decreased leukocyte extravasation and associated with cancer development." (PMID 31877723, 2019). "Notably, the decreased expression of ICAM2 is associated with poor survival in patients with various cancers." (PMID 27556181, 2016). "In contrast, the LPM population (ICAM2+MHC-IIlo) predominates the PMs until 8–9 weeks after ID8 cancer cells inoculation." (PMID 37932814, 2023). "ICAM2, a transmembrane glycoprotein of the immunoglobulin superfamily, regulates immune responses and contributes to the occurrence of some cancers." (PMID 37759298, 2023). "Second, the protein levels of CD44, CD133, CD133high, and CD44high TNBC are indicators of cancer stem cell characteristics that promote metastasis; the protein levels increased in the ICAM2-overexpressing cells compared with vector control." (PMID 37620448, 2023). "Another important mechanism that we identified among the LR biomarkers is the stimulation of LFA-1 (encoded by ITGAL and ITGB2 genes) by ICAM (ICAM2 → ITGAL, ICAM1_ICAM3 → ITGAL, and ICAM3 → ITGB2 in 18, 11, and 8 cancer types, respectively)." (PMID 34430923, 2021). "Downregulation of ICAM2 correlated with poor prognosis in certain cancers (breast, lung, bladder, and soft tissue cancers)." (PMID 27556181, 2016). "Here, cancer cell adhesion is also enhanced by ICAM2 overexpression or by the addition of recombinant ICAM2 protein to culture medium." (PMID 27556181, 2016). "In the present study, wound healing and Matrigel invasion assays were used to show that ICAM2 regulates the migration and invasion capacity of cancer cells." (PMID 27556181, 2016). "We found that neutralizing antibody against ICAM2 strongly promoted cancer cell migration and invasion." (PMID 27556181, 2016). "ERK activation was enhanced by silencing ICAM2 in several cancer cells, compared with parental cells and mock transfectants." (PMID 27556181, 2016). "We analyzed the endogenous protein expression of ICAM2 in a panel of cancer cell lines and found that ICAM2 expression appeared to vary across cell lines." (PMID 27556181, 2016). "In terms of function, we found that the ectopic expression of ICAM2 inhibited cancer cell migration and invasion." (PMID 27556181, 2016). "We also found that ICAM2 overexpression and the presence of recombinant ICAM2 protein enhanced cancer cell adhesion." (PMID 27556181, 2016). "A small-molecule MEK inhibitor reduced the effect of ICAM2 siRNA on cancer cell migration and invasion, suggesting that ICAM2 inhibits cancer cell migration and invasion at least in part through the suppression of the MEK-ERK signaling pathway." (PMID 27556181, 2016).
cancer (continued). "MEK inhibitor, U-0126, reduced the effect of ICAM2 siRNA on cell invasion, suggesting that ICAM2 inhibits invasiveness of cancer cells through suppression of the MEK/ERK signaling pathway." (PMID 27556181, 2016). "Recently, it has been reported, that an increased Icam2 expression on cancer cells enhances the adhesion and reinforces the cytotoxic activity of immune cells such as NK cells, resulting in a reduction of metastasis." (PMID 19812696, 2009). "Recent studies have reported that ICAM2 is deregulated in multiple human cancers." (PMID 37759298, 2023). "Further analyses demonstrated that ERG, a transcription factor, could bind to site 1 of the ICAM2 promoter region to promote ICAM2 transcription, which potentiated the cancer-inhibitory effect of ICAM2." (PMID 37759298, 2023). "The activation of endogenous ICAM2 and exogenous administration of ICAM2 may be used as a treatment option for cancer." (PMID 27556181, 2016). "Moreover, anti-ICAM2 Ab partially abrogated the inhibitory activity of ICAM2 on cancer cell invasion." (PMID 27556181, 2016). "We used the MEK inhibitor, U-0126, to address whether ERK activation is required for ICAM2 siRNA-mediated cancer cell invasion." (PMID 27556181, 2016). "In addition, we demonstrated that silencing endogenous ICAM2 in cancer cells caused a marked increase in extracellular signal-regulated kinase (ERK) phosphorylation levels, suggesting that ICAM2 inhibits migration and invasion of cancer cells by suppressing ERK signaling." (PMID 27556181, 2016). "For example, miR-21, miR-125b, miR-181a, miR-196a, and miR-148b suppress the expression of the apoptosis-related genes caspase-3, intercellular adhesion molecule-2 (ICAM-2), Protein Kinase C Delta (PRKCD), annexin A1 (ANXA1), or DNA methyltransferase 3b (DNMT3B) in a wide spectrum of cancers." (PMID 31174564, 2019). "No dramatic difference in proliferation between ICAM2-transfected cells and the control cells was observed, In contrast, forced ICAM2 expression significantly reduces the migration and invasion capabilities of these cancer cells." (PMID 27556181, 2016). "For naïve T cells, subsequent firm binding was established by ICAM-1 and ICAM-2; however, for cancer cells, this binding could not be blocked by anti-ICAM-1 and ICAM-2 antibodies." (PMID 24766770, 2014).
infection (15 papers, 2009 to 2024). The state of being infected such as from the introduction of a foreign agent such as serum, vaccine, antigenic substance or organism. "More recently, genes associated with NK cell trafficking (CXC3R1 and ICAM2) were shown to be upregulated during the first week of infection and to persist throughout the first month of AHI, suggesting that NK cell homing to lymphoid tissues occurs very early in infection." (PMID 35851334, 2022). "Compared to uninfected endothelial cells, the signal intensities of ICAM-1 and ICAM-2 were elevated by infection with either L. interrogans sv." (PMID 28750011, 2017). "We constructed AAV9‐ENT vectors (based on adeno‐associated virus 9 (AAV9) serotype modification and enhanced the infection efficiency of vascular endothelial cells) carrying Sema3A‐shRNA under the ICAM2 promoter; we then, we delivered these AAV9‐ENT vectors through the tail veins of mice." (PMID 37310417, 2023). "Surprisingly, double ICAM-1 and ICAM-2 knock out mice (herein ICAM-1/2-/- mice) infected with a lab adapted H1N1 influenza A virus fully recovered from infection, elicited potent humoral immunity, and generated normal long lasting anti-viral CD8+ T cell memory." (PMID 36895258, 2022). "Delineation between these two populations during infection could be furthered clarified by staining for other discriminating markers, such as ICAM-2 or TIM-4." (PMID 33767688, 2021). "Percentage of nucleated cells (leukocytes) found circulating in the brain vasculature at day 6 post-infection in mice treated with α−ICAM1, ICAM2, or VCAM1, relative to the isotype control (represented as 100%)." (PMID 35787830, 2022). "Western blotting confirmed the increase in adhesion molecules on endothelial cells following infection, including VCAM-1, ICAM-2, E-selectin, VE-cadherin, and beta-catenin." (PMID 34532298, 2021). "After infection of pBabe-IC2, IC2 FL cells expressed ICAM-2 surface levels similar to those found in HUVEC." (PMID 24593809, 2014). "Additionally, RNA-Seq showed that PRV inoculation during the early stage of infection led to an increase in the transcription/expression of several cellular receptors [e.g., ICAM5, ICAM2, ACAN, and DSCAM] that are known to facilitate bacterial adherence." (PMID 39041808, 2024). "Furthermore, we observed that leukocytes also expressed increased ICAM1 (fivefold) and ICAM2 (twofold), but not VCAM1, upon infection with either strain." (PMID 35787830, 2022).
genetic disease (1 paper, 2021). "Interestingly, there was striking up-regulation of ICAM-2 expression in the airways from patients with CF (a genetic disease characterized by neutrophilic-driven lung inflammation) compared to normal lung." (PMID 34484188, 2021).
immune disorders (1 paper, 2022). "In particular, the SH2B3 locus on chromosome 12 stands out in this regard, with GWAS signals for seven immune disorders colocalizing with three trans-regulated proteins (THPO, ICAM2, CXCL11), all involved in positive regulation of immune system processes (GO:0002684)." (PMID 35078996, 2022).
inflammation (1 paper, 2020). Aberrant reaction of the microcirculation characterized by movement of fluid and leukocytes from the blood into extravascular tissues. "We next assessed the biological relevance of LFA-1, ICAM-1 and ICAM-2 expressions on the development of ILC2-dependent AHR and airway inflammation." (PMID 33193309, 2020).
ICAM2 also shares sentences with these, for which no sentence is quoted: interstitial lung disease (3 papers); endometriosis (2); endothelial dysfunction (2); rheumatoid arthritis (2); type 2 diabetes (2); adenocarcinoma (1); Alzheimer disease (1); autoimmune disease (1); coagulation disorders (1); colon cancer (1); cystic fibrosis (1); fibrosis (1); heart failure (1); Hypercholesterolemia (1); Hyperglycemia (1); Hypertension (1); Hypoglycemia (1); Insulin resistance (1); intraductal papillary mucinous neoplasm (1); leiomyoma (1); meningitis (1); Myocardial fibrosis (1); myocardial infarction (1); oral squamous cell carcinoma (1); osteosarcoma (1); ovarian carcinoma (1); squamous cell carcinoma (1); triple-negative breast carcinoma (1).